STAT3 (signal transducer and activator of transcription 3)
Diseases named in the same sentence as STAT3 in open-access papers (continued):
Sharing a sentence is not in itself a finding about the gene and the disease.
infection (continued). "Consistent with this, our study also revealed an overactivation of the STAT3 pathway in the absence of GR signaling during infection." (PMID 40702267, 2025). "In contrast, the results show that knocking down SOCS3 or SHP-2 did not increase phospho-STAT3 levels during either psarA or psarA:gp130 infection." (PMID 40188438, 2025). "Through this re-localization, STAT3 regulates downstream transcription factors MYB and BLIMP-1 in an inflammation-dependent manner to shape NK cell differentiation under homeostasis and during infection." (PMID 41040338, 2025). "STAT3 was originally described as an “acute phase response factor (APRF)” in that it mediates the effects of interleukin-6 (IL-6) and related cytokines in response to tissue injury, inflammation, and infection." (PMID 38611065, 2024). "Using precision cut lung slices (PCLS) and air-liquid interface (ALI) airway epithelial cell cultures, the authors showed that impaired STAT3 activation in RSV-infected pediatric multiciliated cells increased cell apoptosis and viral shedding, which enhanced the spread of infection." (PMID 39484717, 2024). "Interestingly, EBV upregulated STAT3 and STAT5A levels, in particular between days 4 and 21 post-infection, whereas STAT5B levels were relatively constant." (PMID 38683861, 2024). "Such visualization at later infection timepoints could have skewed the results and the effect of HDAC1 and HDAC2 on IAV-induced STAT3 nuclear translocation." (PMID 39861822, 2024). "Critically, targets of transcription factors known to regulate inflammation (IRF1, STAT1, STAT3) and fibrosis (SMAD2/3, EGR1, TEAD4, YAP1) appeared to be highly induced in the host, consistent with prior reports of infection-dependent induction of pro-inflammatory and pro-fibrotic gene expression." (PMID 36923592, 2023). "IL-6/STAT3 pathway is involved in a non-specific and acute response of innate immune system to pathogen infection." (PMID 37475019, 2023). "Many LCM-associated regulons were not altered by infection (C/EBPβ), while others were lost (RARG and MAF) and others gained (KLF4, STAT3, FOSB, and BHLHE40)." (PMID 36948193, 2023). "tularensis LVS-infection; a significant upregulation of genes involved in RAS pathway including Ccl2, Nfkb, p38 Mapk, Ras, Stat1, Stat3 and Tnf-α; and an upregulated expression of IFN-γ pathway genes such as Bak, Bax, Ifit, Ifn-γ, Irf, Isg, Oas1, Psmb8, Ptpn2, Stat and Tap1." (PMID 37266014, 2023). "Similarly, in a study of infection with F. nucleatum, the expression of MYC, JAK1, and STAT3 was significantly stimulated." (PMID 38248096, 2023). "One possible explanation for higher TIM-3 expression on cDC1 during LD infection is that TIM-3, being an inhibitory receptor, might be restraining cDC1 from exhibiting proinflammatory effects via STAT3." (PMID 37202419, 2023). "Compared to infection with P. aeruginosa PAO1 alone, infection with P. aeruginosa PAO1 combined with AI-2 treatment resulted in significantly increased levels of IL-17A, numbers of Th17 cells and levels of STAT3 in the lung tissues of WT mice (P < 0.05), as well as more serious lung damage." (PMID 36033859, 2022). "Also, the STAT3, AKT1, MAPK9, MAPK14, and CREBBP were identified as host’s infection response regulators of bacterial Hcp in duck." (PMID 36262184, 2022). "The underlying mechanism of SEP was involved in the increased activity of TLR4/STAT3/CD64 signaling in macrophages, and provided some evidence for its potential clinical development as immunoprophylaxis or adjunct antimicrobial agents for infection." (PMID 35370674, 2022). "We observed that p-STAT3 levels were significantly lower in uninfected senescent HeLa and remained lower than its levels in non-senescent HeLa even after infection." (PMID 34746026, 2021).
infection (continued). "Exogenous activation of STAT3 and 6 suppresses host cell ROS production during infection with ROP16-deficient parasites and depletion of STAT6, but not STAT3 or 5a, causes an accumulation of ROS in cells infected with wild-type parasites." (PMID 33653884, 2021). "In non-senescent HeLa cells, infection significantly increased after inhibiting STAT3 activation but was otherwise unperturbed in the presence of other inhibitors." (PMID 34746026, 2021). "Next, we examined the activation of the key kinases p38 MAPK, ERK and the final downstream effector target of JAK1/2 pathway i.e., STAT3 in uninfected non-senescent and senescent cells and at 1h and 16h post-infection." (PMID 34746026, 2021). "Moreover, the immune-suppressive signals, such as suppression of IL21R on STAT3, PI3K mediated inhibition of inflammation by dopamine upon infection, as well as the inhibition of NLRC3 on STING during a steady state." (PMID 34290708, 2021). "Interestingly, blocking p38 MAPK (p38MAPKi) activity in senescent HeLa cells resulted in significantly reduced activation of STAT3 at 4h and 16h post-infection and increased phosphorylation of ERK at early time points (1h and 4h) of infection." (PMID 34746026, 2021). "When we checked phosphorylation levels of STAT1 and STAT3 at 6 h after infection in Vero cells, there was still no prominent effect of HCoV-OC43 infection." (PMID 34835005, 2021). "IL-17-related infection scores are higher in SLT patients than both control groups; moreover, the clinical phenotype of SLT patients is similar to patients with STAT1 and STAT3-mediated IL-17 defects." (PMID 32868758, 2020). "It has been described that a mutation (Tyr 1138 Ser) in tyrosine 1138 residue located in the intracellular domain of LEP-Rb isoform mediates STAT3/SOCS3 signaling, which results in decreased chemokine production and immune cells recruitment at the site of infection in mucosal gut tissue." (PMID 32824322, 2020). "However, in response to infection, male mice exhibited higher expression levels of CXCL2 (KO, 1A3, and 6A2), SAMHD1 (1A0, 1A3), RSAD2, STAT1, and STAT3 (1A0), MYD88 and PSMB8 (1A3), BCL3, BCL10, CCRL2, IFITM2, RTP4, and ZFP36L1 (6A2), compared to females." (PMID 32670284, 2020). "Moreover, both CRT exposure and the release of HSP70/90 and HMGB1were greatly augmented in STAT3‐depleted DU‐145 and PC‐3 cell lines upon NDV/FMW infection." (PMID 32100392, 2020). "On the other hand, STAT3 regulates IFN-γ in both long and short infections." (PMID 32634740, 2020). "Our results showed that up-regulation of STAT3 phosphorylation due to TLT2 overexpression following H37Rv infection was not blocked by pretreatment with anti-IL-6Rα." (PMID 33042115, 2020). "Ultimately, similar STAT3 activation results were observed in CEP-TgROP18I and CEP-TgROP18II infected HaCaT cells at 30 min post-infection, which suggested that both type I and type II ROP18 could activate STAT3 in HaCaT cells at the early stage of infection." (PMID 32767999, 2020). "Under infection and inflammation conditions, interleukin-6 activates the expression of hepcidin through the Janus kinase/signal transducer and activator of transcription 3 (JAK/STAT3) pathway." (PMID 32245010, 2020). "In line with the known role of secreted Salmonella effectors in STAT3 phosphorylation, no phosphorylation signal was detected when infections were carried out with a Salmonella mutant devoid of the SPI1 and SPI2 pathogenicity islands (strain ΔSPI1/2)." (PMID 32071273, 2020). "While JAK1 shows only marginal expression in A549 cells, there was a clear activation of JAK2 (phosphorylation of JAK2 at Y1007/Y1008) and its downstream target signal transducer and activator of transcription 3 (STAT3, phosphorylation at Y705) detectable upon WSN infection." (PMID 32866218, 2020). "However, upon infection with steE mutant bacteria expressing SteE:HA, both GFP-GSK3α and GFP-GSK3β interacted with STAT3." (PMID 31862381, 2020).
infection (continued). "To address the role played by the IL-21/IL-21R signaling axis in CD4+ T cells in host protection after C. rodentium infection, we assessed the bacterial burden, the infection kinetics and survival rates in conditional knockout mice with a CD4+ T cells-specific deletion of STAT3 activity." (PMID 30818341, 2019). "Splenic NK cells were isolated by negative selection at both 24 and 72 h post-infection (hpi) and evaluated for activation of STAT3." (PMID 31552035, 2019). "Together, these data indicate that RSV modulates the IL-21/STAT3 pathway in human memory CD8 T cells, and this could be a mechanism to be further explored to improve the memory response against the infection." (PMID 31780735, 2019). "Our present study demonstrated that translocation of activated STAT1 and STAT3 induced by EV71 infection required KPNA1 in T98G cells, and consistent with a previous study in RD cells, we observed degradation of KPNA1 in T98G cells upon infection." (PMID 31575039, 2019). "For both genotypes, the levels of phospho-STAT1 and phospho-STAT3 are not significantly different 48h after infection." (PMID 29518136, 2018). "To probe for STAT1 or STAT3 roles in IL-6-mediated inhibition of infection, we tested the effect of IL-6 (5 ng/mL, 14 h) on the knockout cells with or without infection with EHDV-TAU (48 h, multiplicity of infection moi = 0.5)." (PMID 29441069, 2018). "However, while ROP16 is reported to induce Y705 STAT3 phosphorylation as early 1.5 h post infection in macrophages, ROP16 did not appear to mediate STAT3 phosphorylation at earlier time points after infection in these cells." (PMID 29036202, 2017). "Tyrosine-phosphorylation of STAT-3 was significantly increased during infection with P. gingivalis and activation by LPS-Pg but not modified during infection with heat-killed P. gingivalis." (PMID 28748038, 2017). "Similarly as STAT3, SOCS3 is expressed in M. tuberculosis-infected human macrophages as early as 3 hours post-infection and remains highly detectable up to 24 hours post-infection." (PMID 27384401, 2016). "Reduced phosphorylation of STAT-3 was also observed in the presence of PD98059, an ERK inhibitor, indicating an involvement of pERK 1/2 in STAT-3 phosphorylation in addition to IL-13-JAK-2 axis during infection." (PMID 27826299, 2016). "The results indicate that STAT3 is not required for terminal plasma cell differentiation or immunoglobulin secretion in response to MHV68 infection." (PMID 27486189, 2016). "Following an acute infection, murine gammaherpesvirus 68 (MHV68) established latency in resident B cells, but establishment of latency was dramatically reduced in animals with a B cell-specific STAT3 deletion." (PMID 27486189, 2016). "Therefore, during the very early stages of infection, EBV uses a cellular mechanism (involving STAT3, caspase 7 and claspin) to block ATR-Chk1 signaling, thereby ensuring that cell proliferation would endure while viral latency gene expression gained traction." (PMID 27458446, 2016). "In the setting of infection of primary B cells by EBV, this rapidly activated STAT3 plays a key role in suppressing the DNA damage response (DDR) to EBV-oncogene triggered replication stress, thereby facilitating B cell proliferation and ultimately establishment of latency." (PMID 27458446, 2016). "While colonic epithelial cells of uninfected mice showed no phosphorylated Stat3, the transcription factor was activated after infection with C. rodentium." (PMID 25799189, 2015). "We also evaluated time points very early after in vitro and in vivo infection, and utilized STAT3 inhibitory approaches that block unphosphorylated and phosphorylated STAT3, not just Tyr-705 activated monomers and dimers." (PMID 25419841, 2014). "In contrast to the cytokine expression in WT mice, the expression of IL-1β and TNF-α in STAT3 KO mice was not longer raised 28 days after infection." (PMID 22675647, 2012).
infection (continued). "Compared to the infected wild-type mice, the mRNA expression levels of IL-1β, IL-6, and TNF-α as well as the number of infiltrating immune cells revealed no distinction in STAT3 KO mice 10 days after infection." (PMID 22675647, 2012). "Infection triggered tyrosine phosphorylation of both JAK1 and JAK2, in addition to STAT3." (PMID 21931552, 2011). "In contrast, MØ infected with ΔROP16 parasites displayed early STAT3 tyrosine phosphorylation, but this response was not sustained and phosphorylation levels dropped to background within 1.5 h of infection." (PMID 21931552, 2011). "Furthermore, the infection data are consistent with the overexpression results, demonstrating that STAT3 activation is reduced when the GBS of SarA is replaced by the GBS of gp130 based on levels of phospho-STAT3 and SOCS3." (PMID 40188438, 2025). "This discrepancy may reflect partial activation of apoptotic machinery that was insufficient to trigger membrane changes detectable by annexin V. Although STAT3 abrogation increased caspase 3 activation, it did not induce apoptosis during infection." (PMID 41115066, 2025). "The significant impact of STAT3 abrogation on infection in the absence of apoptosis indicates that STAT3 may contribute to infection in other ways." (PMID 41115066, 2025). "Therefore, the visualization of STAT3 nuclear translocation in the presence or absence of HDAC1 or HDAC2 expression at the 6 h infection timepoint represents its accurate activation window." (PMID 39861822, 2024). "However, it should be noted that no significant increases in STAT3 phosphorylation (pSTAT3) were detected after 2 h of infection under any of the experimental conditions." (PMID 38612423, 2024). "As shown, we did not detect significant changes in STAT3 nuclear translocation in OKF6/TERT2 cells under any of the studied conditions, which suggests that STAT3 does not participate in the effects observed after infection with the co-culture of P. gingivalis and F. nucleatum at that timepoint." (PMID 38612423, 2024). "However, Ptpn2ΔIEC mice did not induce STAT3 activation in IECs or increase expression of antimicrobial defense molecules after infection, despite normal expression of Il22r1 and Il10r2." (PMID 36810248, 2023). "In general, infection induces uterine contraction, rupture of membrane, cervical softening by promoting changes in prostaglandin, matrix metalloproteinases, or oxytocin receptors through cytokines secretion and the cytokine like IL-6 activate the JAK/STAT3 signaling pathway." (PMID 38019868, 2023). "This suggests that the effect on infection observed upon bafilomycin A treatment is not attributable to the inhibition of endosomal trafficking, but rather to the dephosphorylation and relocalization of STAT3 induced by the inhibitor." (PMID 37830871, 2023). "The VGF dependent upregulation of the non-canonical STAT3 pathway was seen as early as 10-minute post-infection and could still be observed at 8 hpi." (PMID 33529218, 2021). "Immunological parameters normalized and the infection frequency significantly diminished, but non-immunological features of STAT3-HIES remained, including a propensity to recurrent fractures and development of a new pneumatocele, associated with ≤50% donor chimerism." (PMID 33523338, 2021). "Given that p38MAPK, ERK and STAT3 are known to regulate infection in non-senescent cells, we first sought to compare the activation kinetics of these kinases between non-senescent and senescent cells after infection." (PMID 34746026, 2021). "Inhibition of STAT3 had no impact on the overall infection rates of C. trachomatis." (PMID 33785629, 2021). "However, the amount of p-STAT3 at 24 h was similar in NK cells from B6 and B6.Il10−/− mice, indicating that STAT3 activation occurs in NK cells at 24 h and 72 h post-infection, but that early activation is independent of IL-10 production." (PMID 35053151, 2021).
infection (continued). "Thus, the results above from in-depth mechanistic experiments demonstrated that MIR337-3p targeted/depressed upstream TLR4/MYD88 and STAT3 signaling and the downstream VDR antimicrobial pathways of CYP27B1/DEFB4A/CAMP, leading to an enhanced mycobacterial entry/infection and growth." (PMID 34912331, 2021). "Similarly, STAT3 phosphorylation at Y705 and activation by EBV de novo infection has been reported." (PMID 33182552, 2020). "Although it is not well understood if NF-κB and STAT3 are activated during HTLV-1 de novo infection, we speculate that NF-κB and STAT3 are activated, as NF-κB and STAT3-regulated inflammatory molecules, including IFN-γ, IL-1, TNF-α, IL-6 and CXCL10, are produced during HTLV-1 de novo infection." (PMID 33182552, 2020). "However, the relevance of STAT3 activation by Salmonella in the context of a complex, multicell-type infection is unclear, partially due to the lack of suitable model systems." (PMID 32071273, 2020). "In addition to shrimp, an Ec-STAT3 identified from orange-spotted grouper (Epinephelus coioides) is activated and induced to translocate into nucleus following Singapore grouper iridovirus (SGIV) infection." (PMID 31293595, 2019). "Surprisingly, in our study we also observed that more than 18 key genes, including Jak2, Stat3, Stat5a, Pik3r5 and Cish, of JAK-STAT pathway were significantly up-regulated by S. aureus + PG infection, thus indicating that S. aureus + PG treatment might also activate JAK-STAT signaling." (PMID 29304086, 2018). "Similarly, Rift Valley fever virus (RVFV) infection induces STAT3 (pY705) phosphorylation by the viral non-structural protein s (NSs)." (PMID 29543893, 2018). "In addition to this, a mutation (Tyr 1138 Ser) in tyrosine 1138 residue located in the intracellular domain of LEP-Rb isoform mediates STAT3/SOCS3 signaling, which results in decreased chemokine production and immune cells recruitment at the site of infection in mucosal gut tissue." (PMID 29868503, 2018). "In response to infection, CD4+ T cell-specific Stat3−/− mice have increased HSV-1-specific CD8+ T cells that express lower levels of KLRG-1 and IFNγ, suggesting that antiviral CD8+ T cell function relies in part on their cooperation with STAT3-competent CD4+ cells." (PMID 30167845, 2018). "While IL-6 induced strong STAT3 phosphorylation, no phosphorylation was observed in cell infected with either the WT or ΔespO, suggesting that STAT3 phosphorylation is not a direct cell response to infection." (PMID 30365535, 2018). "However, the effect of ROP16 on STAT3 phosphorylation is not noticeable until after 1–1.5 hr post-infection (and this study) and the parasite induces STAT3 activation as early as 2 min post-infection." (PMID 29036202, 2017). "Vaccinia-scarified SCID mice, treated topically prior to infection with an inhibitor of phosphorylated and non-phosphorylated STAT3 (Stattic®), demonstrated larger vaccinia lesions, higher viral titers, and shorter survival post-infection, compared to scarified, vehicle control-treated animals." (PMID 28081250, 2017). "The important role of astrogliosis in the resolution of many neuropathologies is highlighted by findings that the outcomes in SCI and EAE are exacerbated in mice lacking astrocyte STAT3, with increased spread of inflammation, infection, and impaired recovery of function." (PMID 28700615, 2017). "The oncogenic transcription factor Stat3 was down-regulated in both the proximal and the middle section, and the same pattern holds in middle and distal sections for Saa2, a member of the family of APR proteins that is usually up-regulated during infection, tissue damage or inflammation disease." (PMID 26861690, 2016). "Our infections of the stat3f/fCD19Cre/+ mice by the intraperitoneal route did not reveal a generalized defect in germinal center participation or IgG class switching for B cells lacking STAT3." (PMID 27486189, 2016). "In contrast, STAT3 activation did not increase with infection." (PMID 27178303, 2016).